FTO (FTO alpha-ketoglutarate dependent dioxygenase)
Diseases named in the same sentence as FTO in open-access papers (continued):
Sharing a sentence is not in itself a finding about the gene and the disease.
tumor (continued). "Further research showed that FTO promoted the occurrence and development of EC by mediating lipid metabolism, and HSD17B11 could be a key component in mediating FTO-dependent tumor stemness." (PMID 35568876, 2022). "In addition, BNIP3 promotes cancer through demethylation catalyzed by FTO, while ALKBH5 upregulates the expression of NANOG through demethylation of m6A and promotes the aggregation of breast cancer cells in the tumour microenvironment." (PMID 34794452, 2021). "This indicates that, contrary to LINC00022 and FTO, YTHDF2 plays a tumor suppressor role in ESCC." (PMID 34544449, 2021). "While overexpression of FTO slightly increased cell proliferation in HaCaT cells, it did not induce tumor formation in NSG mice, indicating that FTO overexpression alone is not sufficient to induce tumorigenesis." (PMID 33846348, 2021). "However, it is undeniable that the FTO inhibitors CS1 and CS2 with anti-tumor and low side effects derived from the data have great potential in clinical applications." (PMID 34149432, 2021). "According to Rui Su, FTO as a direct target of R-2HG(R-2-hydroxyglutarate is a co-metabolite resulting from the high level of isocitrate dehydrogenase 1/2 (IDH1/2) mutants) and a main mediator of R-2HG-induced anti-tumor effects." (PMID 34281602, 2021). "Based on these, it was speculated omeprazole induced FTO inhibition could increase the transcript level of DDIT3, which is an apoptosis-related tumor suppressor gene downstream of mTORC1 signaling through an m6A-dependent mechanism." (PMID 33393595, 2021). "Furthermore, although demethylases’ expression heterogeneity was observed within each subtype, significant differences in FTO and ALKBH5 expression were found among the main tumor subtypes." (PMID 34683137, 2021). "Furthermore, pharmacological inhibition of eraser FTO impedes GBM growth and tumor initiation while also prolonging the life expectancy of GSC‐engrafted mice." (PMID 34586737, 2021). "Indeed, forced expression of PYCR1 restored the propagation and invasion defects of FTO-depleted BLCA cells, indicating the essential tumor-promoting role of USP18/FTO/PYCR1 signaling network in BLCA." (PMID 33461172, 2021). "We chose some regulators for RT-qPCR validation, and the qPCR results revealed that METTL3, METTL14, and FTO had consistently low expression in 33 paired samples with TCGA data, while YTHDF1 and YTHDF3 showed increased expression in tumor samples compared to adjacent tissues." (PMID 34804948, 2021). "The FTO mRNA and protein levels were higher in OSCC tumor samples than in healthy tissues." (PMID 34378866, 2021). "However, both FTO and ALKBH5 in tumor cells are proved to decrease response to anti-PD-1 blockade immunotherapy." (PMID 34526985, 2021). "M6A modification, FTO and ALKBH5 differed in cellular distribution between tumor samples." (PMID 34683137, 2021). "Meanwhile, omeprazole induced FTO inhibition could increase the transcript level of DDIT3, which is an apoptosis-related tumor suppressor gene downstream of mTORC1 signaling through an m6A-dependent mechanism." (PMID 33393595, 2021). "Stabilized FTO reduced m6A methylation on pyrroline-5-carboxylate reductase 1 (PYCR1) and extended PYCR1 mRNA half-life to promote BLCA cell proliferation and migration in vitro as well as tumor growth in vivo." (PMID 33461172, 2021). "Similarly, two major RNA demethylases, i.e., FTO and ALKBH5, were overexpressed in the tumor samples." (PMID 33062408, 2020). "On the contrary, METTL14, ZC3H13, FTO, and WTAP are low-expressed in tumor tissues." (PMID 32258108, 2020). "However, a most recent study delineates that FTO, which is regulated by SIRT1-induced SUMOylation, functions as a tumor suppressor in HCC." (PMID 32772918, 2020).
tumor (continued). "Furthermore, we also investigated the protein expression levels of m6A-related genes in fresh tumor tissues and the results indicated that the expression level of WTAP and FTO were markedly higher in GC tissues compared with normal control tissues." (PMID 32226518, 2020). "Correspondingly, FTO deletion increases m6A methylation in oncogenes, thus resulting in recruitment of the “reader” binding protein YTHDF2, increased RNA decay, and sensitization of tumor cells to anti-PD-1 treatment." (PMID 32296573, 2020). "Most increased regulators in tumor cases compared to normal cases were YTHDF2 (p < 0.001), FTO (p < 0.001), YTHDC1 (p < 0.001), YTHDC2 (p < 0.001), YTHDF1 (p < 0.001), KIAA1429 (p < 0.001), METTL3 (p < 0.010), WTAP (p < 0.001), RBM15 (p < 0.001), HNRNPC (p < 0.001), and ALKBH5 (p = 0.001)." (PMID 32733931, 2020). "Restored expression of FTO, through reducing m6A levels in mRNA transcripts of its critical target gene PGC‐1α, increases mitochondrial content, ROS production and oxidative damage, with the most important effect of repressed tumour growth." (PMID 30648791, 2019). "Meanwhile, FTO has higher expression in tumor tissues and a negative correlation with P2RX6 expression, but survival analysis has no significantly difference between two groups." (PMID 31159832, 2019). "As well, reduced level of the m6A members METTL3, METTL14, WTAP and FTO but not their mutation and overexpression was tightly associated with cancer progression and poor survival, and these could be developed as novel prognostic markers to predict tumor recurrence." (PMID 30953473, 2019). "D FTO has higher expression in tumor tissues and E survival analysis has no significantly difference between two groups." (PMID 31159832, 2019). "Furthermore, when treating the mice with FTO Inhibitor MA2, the tumor size was significantly reduced." (PMID 29228737, 2017). "FTO inhibition + radiotherapy enhanced tumor control without worsening normal-tissue toxicity; reader targeting (YTHDF1/2) + RT or RT+ICB amplified STING–IFN-I signaling and T-cell priming; METTL3 inhibition combined with venetoclax overcame acquired resistance in AML." (PMID 41280938, 2025). "They explained the mechanism as an FTO inhibitor restrained pyruvate kinase and hexokinase activity and suppressed BC cell glycolysis, partly through lowering the levels of PI3K, p-PI3K, Akt, and p-Akt, which were members of PI3K/AKT signaling pathway and progress tumor growth." (PMID 40630163, 2025). "Furthermore, the multivariate analyses indicated that FTO served as an independent prognostic factor for OS (HR = 0.695, 95% CI, 0.504–0.957, P = 0.026), along with GGT, tumor size, microvascular invasion, tumor encapsulation, and tumor differentiation." (PMID 40316995, 2025). "Heatmap analysis revealed a significant positive correlation between FTO and IGFBP3 mRNA levels (r = .4503) and this was confirmed by western blot analysis, which showed significantly elevated IGFBP3 protein levels in tumour tissues compared with adjacent normal lung tissues." (PMID 40621649, 2025). "Moreover, the overexpression of FTO not only significantly promoted tumor growth (shNC + Vector & shNC + FTO-FLAG, FDR < 0.05), but also reversed the growth inhibition induced by shSRSF6 (shSRSF6 + Vector & shSRSF6 + FTO-FLAG, FDR < 0.01)." (PMID 40712780, 2025). "Second, delivery optimization via antibody-drug conjugates (ADCs) could exploit tumor-specific antigens (e.g. HER2, TROP-2) to localize inhibitors (e.g. FTO or ALKBH5 inhibitors) to cancer cells, leveraging stable linkers and high drug-antibody ratios (DAR) to minimize off-target immune suppression." (PMID 40176140, 2025). "Mechanistic studies revealed that compound 39 could inhibit FTO activity, increase the methylation levels of c-Myc and CEBPA mRNA, and reduce the stability of their transcripts, thereby suppressing related signals and inhibiting tumor progression." (PMID 38711100, 2024).
tumor (continued). "Further investigation revealed that this interesting phenomenon may be related to R-2HG, a metabolite of IDH, compound 39 (R-2HG, FTO IC50 = 133.3 μM) can affect the FTO/m6A/MYC/CEBPA pathway and inhibit tumor proliferation and survival by repressing the expression of FTO." (PMID 38711100, 2024). "Notably, FTO and ALKBH5 may exert opposing effects within tumor contexts, regulated by factors such as tumor type, microenvironment, and cellular status." (PMID 39192357, 2024). "Between 2012 and 2019, researchers developed and identified a series of FTO inhibitors, such as rhein, MO-I-500, methylclofenac (MA), fluorescein, 2-hydroxyglutaric acid (R-2HG), FB23, and FB23-2, which showed significant anti-tumor effects in vitro and in vivo." (PMID 38166832, 2024). "Decreased expression of seven m6A regulators [METTL14, YTHDC2, FTO, ALKBH5, HNRNPA2B1, VIRMA, and RNA-binding motif protein, X chromosome (RBMX)] was evident in OC tissues sample and in the advanced-stage cohort, suggesting crucial roles in tumor suppressors of OC progression." (PMID 38544837, 2024). "Interestingly, FTO and ALKBH5 may act as oncogenes or tumor suppressors in different types of cancer, indicating their diverse roles in tumor progression and metastasis." (PMID 39192357, 2024). "Besides its tumor-suppressive effect in RCC, FTO also exhibited an oncogenic effect." (PMID 38503745, 2024). "Furthermore, by modulating the IL-6/JAK2/STAT3 signal pathway, FTO and APOE may limit the glycolysis of PTC, which could ultimately affect the growth of the tumor." (PMID 36831377, 2023). "For FTO, its expression level was positively correlated with CD8+ T cells, CD4+ T cells, macrophages and neutrophils, which suggested active anti-tumor microenvironment and might explain patients with higher transcription level of FTO possessed significant longer OS time." (PMID 35371987, 2022). "In the drug resistance study of GC cells, omeprazole inhibition of FTO could improve the inhibitory effect of 5-Fu, DDP, and TAX on GC cells as well as enhance the ability of mTORC1 to inhibit autophagy and improve the anti-tumor ability." (PMID 36561529, 2022). "In line with the in vitro findings, FTO inhibition induced growth rates of tumors relative to control tumors, whereas PHF1 overexpression could attenuate the elevated growth, as quantified and compared by the tumor volumes and tumor weight." (PMID 35945194, 2022). "The findings of the current study showed that FTO inhibited expression of APOE through IGF2BP2-mediated m6A modification and may inhibit glycolytic metabolism in PTC by modulating IL-6/JAK2/STAT3 signaling pathway, thus abrogating tumor growth." (PMID 35090515, 2022). "Therefore, microRNA-1,266 may be a tumor-suppressor gene in CRC, which affects the progression of CRC via targeting FTO." (PMID 36263301, 2022). "To explored the potential role of FTO in PCa, we predicted the expression level of FTO in PCa on bioinformatics websites, which yielded that the expression level of FTO in 497 pairs of tumor tissues was significantly lower than that in 52 pairs of normal tissues." (PMID 34787056, 2022). "Small-molecule activators or inhibitors of METTL3, as well as inhibitors of FTO, ALKBH5, and IGF2BP1, showed considerable anticancer effects in some in vitro and animal models of cancer, suggesting that RNA m6A modification has good application prospects in tumor therapy." (PMID 36437944, 2022). "In order to unravel the driving forces behind the markedly changed m6A patterns in the tumor adjacent tissues, we analyzed the expression of proteins related to coordinate m6A modifications by Western blot, including m6A methylation writers (METTL3, METT14) and erasers (FTO, ALKBH5)." (PMID 36172147, 2022). "Additionally, the differences in mRNA levels of METTL3, FTO, and YTHDC2 in the studied cell lines indicate that its expression may vary depending on the tumor localization." (PMID 34207099, 2021).
tumor (continued). "Finally, we assessed the roles of FTO and PYCR1 in xenograft tumor growth in vivo." (PMID 33461172, 2021). "Therefore, the expression levels of 7 m6A regulators (METTL14, YTHDC2, FTO, ALKBH5, HNRNPA2B1, VIRMA, and RBMX) were lower in both the OC tissues and the high-stage group, indicating their potential function as tumor suppressors in OC tumorigenesis and development." (PMID 34631700, 2021). "Moreover, a negative correlation between the expression of FTO and miR-576 (r = −0.68, P = 0.001) was revealed in 20 tumour tissues." (PMID 34725345, 2021). "Additionally, WTAP promotes tumorigenesis by enhancing CDK2 expression and FTO is expression is decreased in clear cell RCC, reducing tumor growth via increasing the expression of PGC-1α, a central regulator of mitochondrial function in the PPARγ co-activator family." (PMID 32513173, 2020). "In addition, we wonder whether dysregulation of FTO or ALKBH5 exists in CRC and contributes to tumor formation or progression." (PMID 32111213, 2020). "Thus, Rhein, MA, or MA2 may induce tumor regression in GBM, or increase ATRA efficacy in AML through inhibiting the RNA demethylase FTO." (PMID 29439529, 2018). "However, the cells used in this study were not tumor cells, and whether the characteristics of the cells changed after the inhibition of FTO with CHTB is unclear." (PMID 35155557, 2022). "In addition, FTO and ALKBH5 could also alter the immune microenvironment of GC tumor cells." (PMID 33718213, 2021). "Interestingly, the expression of FTO was decreased in no metastasis, lower tumor grade and stage." (PMID 32850303, 2020). "In addition, among those differential expression regulators, the expressions of WTAP and FTO exhibited significantly sustained elevated and decreased with the progression of CRC, respectively, suggesting enhanced m6A RNA methylation with the increasing tumor grade." (PMID 32500031, 2020). "Especially, it has not been reported to exert any anti-tumor effect in CRC, thus, we decided to focus on Mupirocin as novel inhibitor of FTO for further studies." (PMID 38600610, 2024). "Unlike FTO, which is involved in the regulation of IFN-γ-mediated cytokine and chemokine pathways, ALKBH5 mainly affects the recruitment of immune cells in tumor microenvironment." (PMID 37264402, 2023). "The analysis indicated that, in comparison to the Normal group, the Tumor group's expression of METTL3 was considerably up-regulated, that of FTO was down-regulated, and those of METTL14 and ALKBH5 were not significantly affected." (PMID 37828232, 2023). "Caveolin-1 depletion did not affect the tumor growth of AGS cells, whereas it completely reversed the FTO-inhibited tumor growth and reduced the tumor weight." (PMID 35064107, 2022). "The specific interactions between hypoxia, FTO, and STRAP are not elaborated and the effects of hypoxia tumor microenvironment on cellular m6A modification levels mediated by other m6A writers, erasers, and readers need further exploration." (PMID 34218271, 2021). "The compared with adjacent non-tumorous tissues, we found a higher level of RBM15, IGFBP1, RBMX, FTO, and ALKBH5 in all five STAD tissues, RBM15, FTO and ALKBH5 were overexpressed in STAD tumor tissues, while the expression of IGFBP1, RBMX was not changed in STAD tumor tissues." (PMID 37019148, 2023). "Furthermore, we analyzed FTO expression in 18 normal tissues (oral mucosa tissues) from healthy donors without areca nut chewing habit and 42 OSCC tumor samples collected from OSCC patients, in which 20 had areca nut chewing habit." (PMID 34378866, 2021). "Interestingly, FTO depletion restored the expression levels of TNF‐α, IFN‐γ, IL‐10, and TGF‐β, but not on IL‐17 in CAL27‐A formed tumor." (PMID 34378866, 2021). "In contrast, the expression of WTAP, FTO, or ALKBH5 was not significantly altered in tumor tissues." (PMID 32175271, 2020).
tumor (continued). "The number of lung tumors derived from FTO knockdown KYSE150 cells did not significantly change; however, AKT3-OE or sh-FTO & AKT3-OE significantly promoted the number of lung tumors compared with that in control cells, suggesting that AKT3 overexpression promoted tumor metastasis in vivo." (PMID 38491196, 2024).
cancer (433 papers, 2010 to 2026). A tumor composed of atypical neoplastic, often pleomorphic cells that invade other tissues. "This establishes a theoretical foundation for investigating how FTO gene polymorphisms influence cancer." (PMID 40391584, 2025). "Recently, an increasing number of studies have identified the influence of FTO gene polymorphisms on cancer." (PMID 40391584, 2025). "This meta‐analysis aimed to clarify the connection between six polymorphisms in the FTO gene and susceptibility to cancer." (PMID 40391584, 2025). "FTO, an m6A demethylase, has been implicated in contributing to the progression of various cancers by up-regulating the expression of multiple oncogenes." (PMID 39990672, 2025). "Although these studies have significantly advanced our understanding of the relationship between FTO gene polymorphisms and cancer risk, our research offers several distinct advantages." (PMID 40391584, 2025). "FTO regulates adipogenesis and fat metabolism through RNA demethylation and has been implicated in the progression of various cancers by promoting cell proliferation, migration, and metastasis 112-114." (PMID 40860194, 2025). "Specifically, the FTO SNP rs9939609 has associations with many cancers, from lung and renal to more common types like breast and prostate." (PMID 40040878, 2025). "Li's meta‐analysis, involving 16,277 cases and 31,153 controls, further elucidated the relationship between FTO polymorphisms and cancer risk." (PMID 40391584, 2025). "Zhao's meta‐analysis specifically explored the relationship between the FTO rs8050136 polymorphism and cancer risk, expanding our knowledge of specific FTO polymorphisms." (PMID 40391584, 2025). "Earlier research has indicated that the FTO rs9939609 polymorphism serves as a risk factor for cancer among Asian populations." (PMID 40391584, 2025). "FTO supports cancer-associated fibroblast-mediated angiogenesis through the activation of early growth response 1 (EGR1) and VEGFA." (PMID 40429638, 2025). "When we conducted a subgroup analysis based on race, the findings indicated an inverse relationship between FTO rs1121980 and cancer susceptibility in Caucasians." (PMID 40391584, 2025). "Fifth, we were unable to gather enough data to assess the relationship between FTO polymorphisms and more specific cancer types." (PMID 40391584, 2025). "FTO has been implicated in the invasion, migration, and proliferation of tumors across several cancers and is influenced by m6A levels." (PMID 39175477, 2024). "In early studies of FTO function that focused on the relationship of single nucleotide polymorphisms (SNPs) with cancer, variable results regarding the association of FTO SNPs with BC have been reported in populations of different ethnic origins." (PMID 39040764, 2024). "In a preponderance of cancer variants, FTO exhibits high expression, thereby fostering cancer progression." (PMID 39449798, 2024). "As the first identified m6A demethylase for removing RNA methylation modification, fat mass and obesity-associated protein (FTO) plays instrumental roles in cancer development." (PMID 38956367, 2024). "As the first Erasers identified, FTO is also implicated in the proliferation and renewal of a variety of cancer cells." (PMID 38711100, 2024). "The association between cancer and dietary fat intake in individuals with different FTO genotypes was assessed using different models of logistic regression." (PMID 37543622, 2023). "FTO is highly expressed in many cancers, and its high expression is positively associated with shorter overall survival." (PMID 37007161, 2023). "The FTO protein is linked to numerous diseases, such as cardiovascular diseases, diabetes, and cancer." (PMID 38203234, 2023). "In RCC, the expression levels of ALKBH5 and FTO are associated with shorter overall and cancer-specific survival after nephrectomy and can be used as prognostic biomarkers." (PMID 38117350, 2023).